GPC3 (glypican 3)
Diseases named in the same sentence as GPC3 in open-access papers (continued):
Sharing a sentence is not in itself a finding about the gene and the disease.
cancer (continued). "Two humanized anti-GPC3 antibody-drug conjugates (hYP7 and hYP9.1b) in the IgG format have been reported to induce antibody-dependent cell-mediated cytotoxicity and complement-dependent cytotoxicity in GPC3-positive cancer cells." (PMID 32575828, 2020). "This gave a hint that GPC3 is somehow involved in cancer cell proliferation." (PMID 33344222, 2020). "Some of these clones have a strong ability to kill cancer cells presenting GPC3 peptide in vitro." (PMID 31024850, 2019). "Taken together, GPC3 may be a crucial molecule in cancer cell biology, and the cell surface GPI-anchored GPC3 might serve as a reservoir and cofactor for paracrine or autocrine growth factors to efficiently transduce their outside-in signaling." (PMID 31510063, 2019). "The function of membrane-anchored GPC3 in these cancers is unknown, but it is likely involved in the neoplastic transformation of HCC." (PMID 31024850, 2019). "Therefore, further studies to understand the molecular mechanism and regulation of GPC3 shedding from cancer cells’ surfaces will be required." (PMID 31510063, 2019). "GPC3 has been described as a biomarker in several other cancer types." (PMID 31100935, 2019). "On the other hand, it is difficult to enhance anti-cancer immune responses and even if immunosuppression is overcome in patients with a low, making it necessary to target not only neoantigens but also shared antigens like glypican (GPC)-3." (PMID 31024850, 2019). "In support of this hypothesis, studies have suggested roles of select GPCs, such as GPC-3 in the growth of several different cancers, including those derived from the pancreas, breast and the liver." (PMID 31391540, 2019). "Finally, immunotherapies targeting these cancers need to be designed such that they preferntially target the core C-terminal GPC3 protein, its heparan sulfate side chains, or their interactome rather than the soluble N-terminal GPC3." (PMID 30873384, 2019). "In contrast, soluble GPC3 is known to suppress the proliferation of cancer cells." (PMID 31510063, 2019). "Summary of clinical trials for cancer immunotherapy targeting GPC3." (PMID 31024850, 2019). "GPC3 has been reported to be a prognostic marker in several other cancer types." (PMID 31100935, 2019). "NK92 cells transduced with the GPC3-specific synNotch receptor could produce the proinflammatory cytokine IL12 (GPC3-Syn-IL12-NK92) in response to GPC3 antigen expressed in cancer cells." (PMID 31921693, 2019). "This alternate loading of cancer cell derived exosomes may in turn contribute to our observation of the accumulation of GPC3 in GEA cancer cells." (PMID 31100935, 2019). "Since our molecular analyses indicated an activation of stemness in the SL region, we next assessed the gene expression levels of specific HCC/differentiation markers (AFP, GPC3, albumin) as well as the selected (cancer-) stemness markers (EpCAM, CD133, CK19) and pluripotency genes (NANOG)." (PMID 28415775, 2017). "We have demonstrated that GPC3-redirected CAR-T cells could also have potent antitumor activities in other cancer types in addition to HCC." (PMID 28881778, 2017). "Thus, we propose that the anti-GPC3 BiTE will have similar antitumor activities on these GPC3-positive cancer types." (PMID 28881778, 2017). "This suggests that analyzing GPC3 levels may aid in the early detection of cancer, in particular signet ring cell subtype." (PMID 27259271, 2016). "These clones exhibited cytotoxic activity against cancer cells expressing GPC3 endogenously." (PMID 25354479, 2015). "Based on the close relationships between GPC3, miR-96-5p, -182-5p, and cancers, we made a hypothesis that miR-96-5p and/or -182-5p might regulate GPC1 expression in the development of PC." (PMID 24736782, 2014). "Contrarily, GPC3 expression stimulated cancer cell growth in vitro." (PMID 24992906, 2014). "Recently, GPC1 and GPC3 were found to be predictor and target for some cancers, including PC." (PMID 24736782, 2014).
cancer (continued). "Adoptive transfer of GPC3 peptide-specific CTLs may also be available for other GPC3-expressing cancers." (PMID 25189159, 2014). "The exact role of GPC3 on cancer stem cells therefore needs further investigation." (PMID 22606345, 2012). "GPC3 is a recently noted HCC cancer marker, where it was elevated in 6 out of 7 patient samples." (PMID 15826317, 2005). "However, GPC3 exerts both promotive and inhibitory roles in cancer development." (PMID 40422229, 2025). "Therefore, it has been speculated that GPC3 knockdown could suppress cancer cell growth and metastasis." (PMID 35456649, 2022). "The F3 peptide targeting GPC-3 could distinguish GPC-3 positive tumors in different cancer types." (PMID 34150644, 2021). "The molecular mechanism of action of GPC3 in cancer remains unclear." (PMID 34112123, 2021). "Furthermore, GPC3 might also be used as a serum biomarker and is exploited for different targeted cancer therapy approaches." (PMID 32984308, 2020). "Thus, regulation of this X-linked gene may be not only age and tissue-specific but also gender-dependent and there are likely multiple means by which GPC3 becomes aberrantly deregulated in cancer." (PMID 30873384, 2019). "Thus, to elucidate whether an anti-GPC3 BiTE could also eliminate GPC3-positive cancer cells in an antigen-dependent manner, in this study, we performed in vitro and in vivo experiments." (PMID 28881778, 2017). "However, studies have also demonstrated that GPC3 plays a role in the development of cancer." (PMID 29113314, 2017). "GPC3 plays a negative role in cell proliferation, and its depletion may contribute to cancer progression, although results for tumors originating from tissues expressing GPC3 in the embryo only, suggest its expression tends to occur together with malignant transformation." (PMID 23327652, 2013). "The potent anti‐cancer cytotoxicity of these CAR‐T cells was confirmed against HepG2 cells, which express a high level of GPC3." (PMID 41267637, 2025). "In contrast, GPC3 and ROBO1 were mainly expressed in the cytoplasm of cancer cells, although some expression patterns on the cell membrane of cancer cells were observed." (PMID 40076777, 2025). "They identified CK19 and CA19-9 as highly sensitive markers for iCCA, and Glypican 3 and Hep Par 1 for HCC, with sensitivities reaching 100% in detecting these cancers." (PMID 39857748, 2025). "The glypican 3 gene (GPC3) emerges as a promising target for CAR-T therapy, being a proteoglycan highly expressed in various cancers, including HCC." (PMID 38791916, 2024). "This component features COL10A1, ITIH5, ADIPOQ, ADAMTS5, GPC3, SFRP1, and RARRES2 genes, pointing to their involvement in cancer-related cellular structures." (PMID 38253993, 2024). "AED is a carcinoma with tubulopapillary growth of columnar cells with clear cytoplasm expressing oncofetal proteins, including AFP, GPC3, and/or SALL4." (PMID 38851063, 2024). "For HCC model, markers including CK8, CK18, HepPar-1, Arg-1, AFP, HSP70, GPC3, CEA, CD24, CD133 and EpCAM can be used to identify cancer type and cancer progression." (PMID 37188191, 2023). "Because of the differential expression of several antigens (e.g., CD19, BCMA, GD2, GPC3, and mesothelin) on certain cancer cells, CAR-engineered T (CAR-T) cells specific for these antigens have exhibited great potential in cancer immunotherapies." (PMID 36463401, 2023). "Using the cancer cell line encyclopedia (CCLE) database, we found that the expression levels of GPC3 and PEG10 were high in HepG2 cells and low in SK-Hep-1 cells." (PMID 37932427, 2023). "Transfected cell phenotype was verified prior to in vivo engraftment and the results showed that IL-17 constitutive expression up-regulated cancer cell and CSC markers (Gpc3 and Cd133) as compared to control cells." (PMID 35342340, 2022).
cancer (continued). "Our research of β-catenin pathways in HBL patients revealed that the β-catenin-TCF4-CEGRs/ALCDs pathway accelerates the proliferation of cancer cells and increases the expression of many oncogenes, including AFP and GPC3." (PMID 36551548, 2022). "The obtained results showed that tumors from LPC pIL-17 have a significant increase in cancer cell and CSC markers (Cd133, Klf4, Thy1, Ck19, Afp and Gpc3) when compared to tumors from LPC pEmpty." (PMID 35342340, 2022). "CD133, a kind of cancer stem cell (CSC) antigen, together with glypican-3 (GPC3) has been proved to be highly expressed in HCC cells and both of them are used as targets to generate chimeric antigen receptor (CAR) T cells." (PMID 35879685, 2022). "On the other hand, if a well-differentiated carcinoma consists of what appear to be hepatocytes, then an appropriate panel would include arginase-1, HepPar1, pCEA (or CD10), and glypican-3, as α-fetoprotein has very low yield in well-differentiated HCC." (PMID 35954333, 2022). "In order to achieve better results with CAR therapy, increasing the number of GPC3-CAR and improving the binding rate of CAR to GPC3 become crucial when GPC3 expression is certain in cancer cells." (PMID 34261411, 2021). "Glypican 3, also known as GPC3, is a cancer fetal glycoprotein that is attached to cell membranes via glycophosphatidylinositol anchors." (PMID 34926458, 2021). "Specifically, increased expression of GPC3, DLK1, and HMGA2 are genes that define the driving pathways of HB, and these genes have also been previously reported as cancer stem cell markers in HB7,38." (PMID 34497364, 2021). "Cancer vaccines based on TAAs, such as prostatic acid phosphatase, NY-ESO-1 (cancer/testis antigen), MAGE-A3, and glypican 3, were shown to be immunogenic and induced clinical responses in a subset of patients." (PMID 33961792, 2021). "Furthermore, GPC3 might be a target for cancer immunotherapy in patients with HCC." (PMID 33675149, 2021). "Phase I/II clinical trials suggested that GPC3 peptide vaccine is effective in inducing cytotoxic T lymphocyte (CTL) killing cancer cells, reducing RFS, and improving OS, particularly in patients with GPC3-overexpressing HCC." (PMID 34975896, 2021). "Here, we report a phase I study of cancer vaccination using a combination of two multi-HLA-binding peptides, HSP70 and GPC3, and the novel immune adjuvants combination of Poly-ICLC and hLAG-3Ig for patients with metastatic GI cancers." (PMID 32219501, 2020). "Throughout this review, we focused on few GPI-anchored proteins (MSLN, Glypican-3, CEA, DAF, and MAC-i), with these proteins overexpressed in many cancers." (PMID 33344222, 2020). "In summary it seems that there is great potential for ADCs targeting GPC3 and CD24 in HCC, given their high, selective expression in these cancer cells, and the promising results in preclinical evaluations." (PMID 32575828, 2020). "The expression levels of exosomal proteins, such as CD63, CEA, GPC-3, PD-L1 and HER2, were used to classify different cancer cell lines." (PMID 32802193, 2020). "We performed a multicenter clinical trial that included GPC3-positive refractory pediatric cancer cases (UMIN Clinical Trials Registry: 000006357); 18 patients received GPC3 peptide vaccination." (PMID 31024850, 2019). "Glypican-3 (GPC3) of heparin sulfate proteoglycans, specifically overexpressed in HCC (>80%), is a promising cancer immunotherapeutic target." (PMID 31231341, 2019). "In our clinical trials of GPC3 peptide vaccine, we successfully established multiple types of GPC3 peptide-specific CTL clones derived from the peripheral blood and cancer tissue of vaccinated patients." (PMID 31024850, 2019). "As GPC3 is upregulated exclusively in HCC, it has been used as an immune-specific target for cancer immunotherapy." (PMID 30297672, 2018).
cancer (continued). "Previously, we demonstrated that glypican-3 (GPC3) is highly expressed in HCC, and that GPC3 induces oncogenicity and promotes the growth of cancer cells through IGF-1 receptor (IGF-1R)." (PMID 29113314, 2017). "Currently, the mechanism of Glypican-3 shedding into the extracellular space and sera is of general interest, and the possibility of using GPC3 as a serological marker in different cancer types is under investigation." (PMID 26517809, 2015). "Clonogenicity is one of the fundamental properties of cancer stem cell, which was measured in PLC CD90+GPC3+(GPC3−) and PLC CD90+GPC3+(SSC) cells." (PMID 22606345, 2012). "In vitro cell experiments showed that the mRNA and protein levels of APOD, GPC3, and SERPINE1 were upregulated in the STAD cell line and that APOD knockout significantly reduced cancer cell proliferation, migration, and invasion levels and increased the apoptotic capacity of the STAD cell line." (PMID 41438490, 2025). "Previous studies have suggested that genes located in this region, such as ZNF217, GPC3, and CYP2S1, could contribute to the development and progression of cancer." (PMID 40354349, 2025). "Successful preclinical NIR-PIT studies against cancer and cancer-stem like cell antigens have been performed against more than 20 different molecular targets expressed on different cancers including EGFR, HER2, PSMA, CD25, GPC3, mesothelin, CD133, CD44, CEA, DLL3, PD-L1, and others." (PMID 38658501, 2024). "In the case of GPC3, two humanized mAbs (hYP7 and hYP9.1b) in the IgG format have been reported to induce antibody-dependent cell-mediated cytotoxicity (ADCC) and complement-dependent cytotoxicity (CDC) in GPC3-positive cancer cells." (PMID 38473265, 2024). "While TSAs, including alpha-fetoprotein (AFP), glypican-3 (GPC3), and melanoma-associated gene 1 (MAGE-1) in HCC, are predominantly cancer-centric, their presence, albeit in lower quantities, is not exclusive to cancer cells." (PMID 39295859, 2024). "GPC3, a carcinoembryonic antigen, overexpressed in HCC and involved in Wnt‐dependent cell proliferation, is a target for CAR (hYP7)‐T cells, which can eliminate GPC3‐positive HCC cells through perforin‐ and granzyme‐mediated apoptosis or Wnt signalling reduction in cancer cells." (PMID 38935536, 2024). "In this respect, two targets have been explored so far: the cell surface membrane-bound glypican-3 (GPC3), a heparan sulfate proteoglycan protein, and the cell membrane-bound CD24, which is a mucin-like molecule that is overexpressed in a range of human carcinomas, including HCC." (PMID 38473265, 2024). "In a phase I clinical trial focusing on Glypican-3 (GPC3), a significant HCC-associated antigen, as a promising target for heavily treated HCC patients CT017 CAR T cells co-expressing CAR-GPC3 and RUNX3 were engineered to induce CD8+ T-cell infiltration within the cancer microenvironment." (PMID 37999131, 2023). "These antibodies are designed to specifically target and kill GPC3-expressing cancer cells, while sparing normal liver cells that do not express GPC3." (PMID 38173713, 2023). "Anchoring HN3 to the membrane of the EVs through LAMP2, drastically increased the specific homing of HLC9-EVs to GPC3+Huh-7 cancer cells rather than co-cultured GPC3−LO2 cells." (PMID 37202772, 2023). "Some of these have been found altered in cancer, for example, FAP (seprase) or glypican-3." (PMID 36230486, 2022). "Furthermore, hnRNPA3 combined with GPC3 can effectively differentiate between HGDN and eHCC, implying the aptitude of hnRNPA3 to differentially diagnose cancer." (PMID 35879279, 2022). "GPC3 also interacts with glucose metabolism of HCC and increases the expression of HIF-1α protein, which in turn upregulates glucose uptake and lactate production and promotes cancer growth." (PMID 36077433, 2022). "However, the antibody-mediated immunological therapy by GPC3 antibodies was ineffective in treating HCC, and the reason was the specificity against cancer." (PMID 36139670, 2022).
cancer (continued). "Glypican‐3 (GPC3) is a cell surface biomarker that is overexpressed in foetal liver and early‐stage cancer but not in the healthy adult liver." (PMID 35152538, 2022). "Nakatsura and coworkers demonstrated 5-fold greater GPC3 mRNA expression in HCC cancer tissues than in noncancerous adjacent tissues in 16/20 samples." (PMID 36077433, 2022). "There are growing reports using nanobody-based immunotoxins to treat cancers by targeting a variety of antigens such as glypican-3, glypican-2, EGFR, HER2, VEGFR2, CD7 and CD38, which indicates the great potential of nanobody-based immunotoxins for cancer therapy." (PMID 36435809, 2022). "In this study, we identified that circulating miR-375-3p, miR-193a-5p, and miR-1228-5p have potential as predictive biomarkers of response to GPC3 peptide vaccine therapy, and these three miRNAs are not broadly upregulated in cancer tissue." (PMID 33535558, 2021). "A recently developed bifunctional antibody named GPC3-targeted TRAB (T cell-redirecting antibody) has shown immunotherapeutic promise even in non-HCC cancers that express low but distinct levels of GPC3 and is currently in phase I trial." (PMID 33878524, 2021). "Meanwhile, by optimizing the structures, the expression of GPC3-CAR on the cell surface was increased, thereby improving the affinity and tumoricidal efficiency of CAR cells, and providing a novel option for the treatment of cancer." (PMID 34261411, 2021). "Our results showed that 32A9-mPE24 selectively inhibited the growth of GPC3-positive cancer cells with an IC50 value of 0.68 nM but had no obvious effect on GPC3-negative cells." (PMID 32746924, 2020). "In addition, alkaline phosphatase (ALP), glypican-3 (GPC3), and carcinoembryonic antigen (CEA) have been identified as biomarkers of cancers." (PMID 31118109, 2019). "The third generation of GPC3-targeted CAR T-cells was prepared by employing lentiviral transduction, which could efficiently kill GPC3-positive cancer cells in vitro and eradicated HCC xenografts expressing high level of GPC3 in vivo." (PMID 29796190, 2018). "Our previous study and the data from the present study indicated that GPC3 is not expressed in any normal tissues examined and is a cancer-specific antigen." (PMID 28881778, 2017). "GPC3 was positively expressed in 78.05% (32/41) of the HCC tissues but none of the para-carcinoma tissues." (PMID 28852111, 2017). "According to IHC and western blot assays, we determined that the residual cancer tissues were almost completely composed of GPC3-negative LSCC cells." (PMID 26684028, 2016). "In addition, the overexpression of GPC-3 specifically in human HCC has been reported, and DC expressing GPC-3 induced protective immunity against highly meta-static cancer." (PMID 22971679, 2012). "Another recent study demonstrated that GPC3 acts as a negative regulator of cell proliferation, but this mechanism may be defective in HCC and thereby cancer cells are unresponsive to over-expressed GPC3 signal." (PMID 22606345, 2012). "In fact, GPC3 may be reactivated in HCC as frequently as AFP, which has been used extensively as a marker of this cancer." (PMID 22087143, 2011). "For example, the expression levels of GPC3 varies greatly among HCC cell lines from diverse origins, and the activation status of other oncogenic-related signaling pathways and the expression levels of related signaling molecules can also fluctuate significantly across different cancer cells." (PMID 40422229, 2025).